FRG1BP (FSHD region gene 1 family member B, pseudogene)
Synonyms: bA348I14.2; formerly C20orf80; FRG1B
Gene: Transcribed unprocessed pseudogene on chromosome 20 (30,377,372 to 30,399,257, forward strand). Ensembl gene ENSG00000149531.
Diseases named in the same sentence as FRG1BP in open-access papers:
FRG1BP is named in the same sentence as 4 diseases in open-access papers, as found by Europe PMC text mining. Sharing a sentence is not in itself a finding about the gene and the disease. The quoted sentences say what the papers report.
ocular sarcoidosis (1 paper, 2024). A leading cause of inflammatory eye disease is sarcoidosis. "FRG1BP (previously known as C20orf80, FRG1B) has been found to be associated with body weight, body height at birth and ocular sarcoidosis phenotypes." (PMID 38052982, 2024).
prostate carcinoma (1 paper, 2022). A carcinoma that arises from epithelial cells of the prostate gland. "In SC3, FRG1BP, a gene previously associated with prostate cancer, was mutated in ~ 50% of samples in SC3 compared to less than 15% of samples in other clusters." (PMID 35439935, 2022).
tumor (1 paper, 2016). "The array data showed that 16 of the 18 selected DMRs were hypermethylated and two regions, FRG1BP and CTAGE15, were hypomethylated in primary tumors compared to tumor-adjacent normal lung tissue." (PMID 27782156, 2016).
FRG1BP also shares sentences with these, for which no sentence is quoted: cancer (1 paper).